RN7SL615P (RNA, 7SL, cytoplasmic 615, pseudogene)
Gene: Miscellaneous RNA gene on chromosome 20 (41,290,280 to 41,290,577, reverse strand). Ensembl gene ENSG00000263989.
Homologues: Orthologues: chimpanzee Metazoa_SRP (99% identical), macaque Metazoa_SRP (94% identical). Paralogues in human: RN7SL2 (86% identical), RN7SL3 (85% identical), RN7SL1 (84% identical), RN7SL126P (82% identical), RN7SL296P (81% identical), RN7SL797P (81% identical), RN7SL147P (81% identical), RN7SL665P (80% identical), RN7SL769P (80% identical), RN7SL804P (80% identical), RN7SL856P (80% identical), RN7SL88P (80% identical), and 704 more.